TNFRSF1B (TNF receptor superfamily member 1B)
Diseases named in the same sentence as TNFRSF1B in open-access papers (continued):
Sharing a sentence is not in itself a finding about the gene and the disease.
COVID-19 (21 papers, 2021 to 2025). A disease caused by infection with severe acute respiratory syndrome coronavirus 2. "Monocytes from patients with COVID-19 express high levels of genes associated with inflammation including IL17RA, JAK-STAT-associated gene STAT6, and inflammatory protein-encoding genes TNFRSF1B and ANXA2." (PMID 36992700, 2023). "TNFRSF1B showed consistent expression changes in AD or AD-related pathologies, as well as in COVID-19 patient CSF samples." (PMID 34108016, 2021). "Notably, the expression of TNF receptor superfamily member 1B (TNFRSF1B) consistently showed changes in cerebrospinal fluid (CSF) samples obtained from patients affected by both COVID-19 and AD." (PMID 38259635, 2023). "In fact, patients with COVID-19 presented the upregulation of T cell markers, such as CD4, CCL21, CD48 and TNFRSF1B/TNFR2." (PMID 37047248, 2023). "Our study found that COVID-19 patients have upregulated pathways in apoptotic signaling pathways and response to virus/viral process, including genes TNF, TNFAIP3, TNFSF10, TNFRSF1B, TNFRSF1." (PMID 37949875, 2023). "We observed increased expression of TNFRSF1B, also known as TNF receptor 2 (TNFR2) in the Classical monocytes and NK cells during active COVID-19." (PMID 36532041, 2022). "It is also notable that many of the transcriptional signatures, including RHOB, MPP6, TNFRSF1B, ITGB2, and ZEB2 elevated in AM2 from COVID-19 patients have also been detected as transcriptional markers of AM B cells." (PMID 35899045, 2022). "Several AD markers (CXCL10, TNFRSF1B, SPP1, TGFB1, GSTM3, and NKTR) have significantly altered expression in COVID-19 patients." (PMID 34108016, 2021). "We identified several AD marker genes (e.g., NKTR, GSTM3, TGFB1, TNFRSF1B, SPP1, and CXCL10) which may provide insights into the shared pathobiology of cognitive dysfunction in COVID-19 and AD." (PMID 34108016, 2021). "In CSF, innate immune genes SPP1, CXCL10, and TNFRSF1B are differentially expressed in COVID-19 vs. non-COVID-19 patients." (PMID 34108016, 2021). "Within the network, we suspected that the 6 ceRNA subnetworks (i.e., MSTRG.119845.30/hsa-miR-20a-5p/TNFRSF1B, MSTRG.119845.30/hsa-miR-29b-2-5p/FCGR2A, and MSTRG.106112.2/hsa-miR-6501-5p/STAT3) may play a crucial role in the development of COVID-19." (PMID 33833618, 2021). "Several factors such as soluble TNF receptor II (TNFRSF1B) and von Willebrand factor (VWF) were found to increase with COVID-19 regardless of pregnancy status." (PMID 37016066, 2023).
melanoma (21 papers, 2014 to 2025). A malignant, usually aggressive tumor composed of atypical, neoplastic melanocytes. "However, the association of TNFRSF1B expression/TNFR2 levels, miRNA-1271, and TNFRSF1B c.*922C>T SNV with melanoma cell proliferation should be investigated by additional functional studies." (PMID 38474115, 2024). "Thus, NK cluster 01 subtype cells have the greatest potential for regulating CM malignant cells through the tumor necrosis factor (TNF)–TNFRSF1B axis, suggesting that NK cluster 01 cells may respond to melanoma cells by producing proinflammatory cytokines, including IFNγ and TNF." (PMID 41357561, 2025).
Obesity (21 papers, 2005 to 2026). Accumulation of substantial excess body fat. "Among all common DEGs, three genes (TNFRSF1B, CACNA1A, and AKT1S1) were found to be associated with obesity-related pathways from the Kyoto Encyclopedia of Genes and Genomes (KEGG) pathway database." (PMID 36499541, 2022). "Furthermore, it has been proposed that polymorphism of the TNFR2 gene (TNFRSF1B) may contribute to the pathogenesis of several metabolic disorders, including obesity and insulin resistance." (PMID 38486041, 2024). "PCOS group also had a higher expression of TNFRSF1B genes related to hyperlipidemia and insulin resistance, which further fuel the PCOS by inducing obesity." (PMID 40790236, 2025).
Stroke (18 papers, 2008 to 2025). Sudden impairment of blood flow to a part of the brain due to occlusion or rupture of an artery to the brain. "Our results indicate that Tnfrsf1a and Tnfrsf1b mRNAs are robustly upregulated in the early stage of ischemic damage in both age groups, but its expression was robustly increased by day 14 post-stroke in the aged brains only." (PMID 24672479, 2014). "The non-canonical pathway integrates signals from a subset of TNF receptor family members including Tnfrsf1a and Tnfrsf1b, both known to be involved in the inflammatory responses to stroke." (PMID 23251410, 2012). "Furthermore, female MMP-3 KO stroke brains showed decreased expression of apoptosis signaling genes Casp6, Tnfrsf1b, Tnfrsf1a, and Tnf, and downregulated expression of matrix metalloprotease genes Mmp14, Mmp9, and Mmp11." (PMID 39000490, 2024). "Female MMP-3 KO stroke brains showed downregulation of the macrophage classical activation signaling genes Tnf and Tnfsf9, and decreased expression of the acute phage response genes Tnfrsf1a, Jun, Tnfrsf1b, Il6, Tnf, and Fos." (PMID 39000490, 2024). "Genes related to inflammation such as Ccl5, Cxcl5, Il1a, Tnfsf10, Nfkb1, Tnfrsf1b, Ccr7, Tnfrsf9, Ccl7, Il1b, Il6, and Ccl24 were also downregulated upon MMP-3 KO in male stroke brains." (PMID 39000490, 2024). "Tnfrsf1a, Tnfrsf1b, and Nfkb2 are known to be involved in inflammatory responses to stroke via noncanonical I-kappa B kinase/NF-kappa B cascade." (PMID 29516010, 2018). "In our experiments, no obvious sex-dependent differences could be detected in microglial Tnfrsf1b expression levels after stroke, suggesting that the sexual dimorphism observed is not dependent on TNFR2 levels themselves, but it is likely due to different mechanisms." (PMID 38142915, 2024).
asthma (17 papers, 2012 to 2025). "Proteins TCN2,TNFRSF1B and C10orf54 were positively associated with the development of asthma (B>0); proteins PDGFD,INHBC and ANXA7 were negatively associated with the development of asthma (B<0)." (PMID 39318474, 2024).
heart failure (17 papers, 2005 to 2025). Inability of the heart to pump blood at an adequate rate to meet tissue metabolic requirements. "On the contrary, Tnfrsf1b (gene encoding TNFR2) genetic deficiency exacerbated heart failure and increased the lethality of TNF-α overexpressing mice pointing to the cardioprotective role of TNFR2." (PMID 33053859, 2020).
Sepsis (17 papers, 2012 to 2026). Sepsis is defined as life-threatening organ dysfunction caused by a dysregulated host response to infection. "However, up to now, only one case control study investigated associations between TNFRSF1A and TNFRSF1B polymorphisms and sepsis susceptibility." (PMID 23029405, 2012). "The objective of this study was to investigate whether genetic variation in TNF, LTA, TNFRSF1A and TNFRSF1B was associated with susceptibility to or death from severe sepsis in Chinese Han population." (PMID 23029405, 2012). "However, to date, only one study investigated the role of TNFRSF1A and TNFRSF1B polymorphisms in sepsis susceptibility and mortality." (PMID 23029405, 2012). "Ten SNPs in TNF, LTA, TNFRSF1A and TNFRSF1B were genotyped in samples of patients with severe sepsis (n = 432), sepsis (n = 384) and healthy controls (n = 624)." (PMID 23029405, 2012). "Therefore, our results cannot exclude variant associations with weaker effects between severe sepsis and the other three candidate genes (LTA, TNFRSF1A, TNFRSF1B)." (PMID 23029405, 2012). "Association analysis of SNPs in TNF, LTA, TNFRSF1A and TNFRSF1B between survivors and non-survivors of severe sepsis patients." (PMID 23029405, 2012). "Considering the important role of TNF-α, LT-α, TNFR1 and TNFR2 in the pathogenesis of severe sepsis, we hypothesized that genetic variation in TNF, LTA, TNFRSF1A and TNFRSF1B might be associated with susceptibility to and outcomes from severe sepsis in Chinese Han population." (PMID 23029405, 2012).
systemic lupus erythematosus (15 papers, 2007 to 2025). An autoimmune multi-organ disease typically associated with vasculopathy and autoantibody production. "TNFRSF1A (TNFR1) expression was significantly higher in group 2 lupus participants compared with group 1, and TNFRSF1B (TNFR2) followed a similar insignificant trend." (PMID 39688922, 2024). "Together, common characteristics of lupus appear to be upregulation of members of the IL-1 family such as IL-1α and IL-1β and IL1R2, of the TNF/death receptor family such as TNF receptor II (TNFRSF1B), TRAIL (TNFSF10), and its decoy receptors, and a gene signature of IFN-α/β-regulated genes." (PMID 19884985, 2009).
Crohn disease (14 papers, 2007 to 2024). A gastrointestinal disorder characterized by chronic inflammation involving all layers of the intestinal wall, noncaseating granulomas affecting the intestinal wall and regional lymph nodes, and transmural fibrosis. "In addition, our previous work has confirmed the value of TNFRSF1B in the prediction of secondary LOR to IFX in Crohn's disease, indicating that other predictive genes of PNR may be equally applicable to secondary LOR." (PMID 34650991, 2021). "In Crohn’s disease, we reported that SNPs in TNFα and receptors (TNFRSF1A/TNFRSF1B) benefited intracellular MAP-survival, increased infection, and elevated inflammatory response mimicking the poor response to anti-TNFα treatment in some patients." (PMID 31817071, 2019). "In our previous study, we identified the TNFRSF1B SNP variation as a predictor for secondary non-response to IFX in Crohn's disease." (PMID 34650991, 2021).
Alzheimer disease (12 papers, 2011 to 2025). A progressive, neurodegenerative disease characterized by loss of function and death of nerve cells in several areas of the brain leading to loss of cognitive function such as memory and language. "This longitudinal study evaluated whether the TNFRSF1B gene encoding TNFR2 and levels of its soluble form (sTNFR2) affect Alzheimer disease (AD) biomarkers and clinical outcomes." (PMID 33716716, 2021).
Hypertension (10 papers, 2005 to 2025). The presence of chronic increased pressure in the systemic arterial system. "We also identified genetic variants associated with metabolic syndrome, hypertension (rs1805762 in M6PR), and increased body weight (rs5746059 in TNFRSF1B)." (PMID 35899193, 2022). "Similarly, upregulated TNFRSF1B was reportedly strongly associated with hyperandrogenism in PCOS and metabolic disorders, including insulin resistance, hypertension, and hyperlipidemia, highlighting the role of inflammatory cytokines in the pathogenesis of PCOS." (PMID 40790236, 2025).
leukemia (10 papers, 2018 to 2025). A malignant (clonal) hematologic disorder, involving hematopoietic stem cells and characterized by the presence of primitive or atypical myeloid or lymphoid cells in the bone marrow and the blood. "Specifically, knockdown of YTHDF2 was found to lead to the upregulation of TNF receptor superfamily member 1b (TNFRSF1B), which encodes TNF receptor 2 (TNF-R2), by extending the half-life of m6A-modified TNFRSF1B transcripts in leukemia cells." (PMID 35382893, 2022). "Taken together, our findings suggest that HHT enhances the interaction between EWSR1 and YTHDF2, thus inhibiting the recognition of the m6A‐modified target genes TNFRSF1B and HMOX1, ultimately leading to apoptosis in leukemia cells." (PMID 41472850, 2025). "Our findings revealed that HHT significantly increased the m6A modification levels of TNFRSF1B and HMOX1 mRNAs in leukemia cells." (PMID 41472850, 2025). "CD74, TNFRSF1B, and ADAM8 all have important roles in the immune system and have enrichment for mRNA expression on candidate cells of origin for NHL and leukaemia." (PMID 38750076, 2024).
pancreatic cancer (10 papers, 2019 to 2025). "In addition, exosomes from pancreatic cancer cells have also been proven to induce osteoclast differentiation via the miR125a-5p/TNFRSF1B pathway." (PMID 36522691, 2022).
gastric cancer (9 papers, 2016 to 2026). A primary or metastatic malignant neoplasm involving the stomach. "The upregulation of Tnfrsf1b, which belongs to the TNF receptor superfamily, has also been found in gastric cancer tissues, and Tnfrsf1b can promote colorectal carcinogenesis." (PMID 33042984, 2020).
lymphoma (9 papers, 2015 to 2024). A malignant (clonal) proliferation of B- lymphocytes or T- lymphocytes which involves the lymph nodes, bone marrow and/or extranodal sites. "The region encompasses the coding sequences of MTOR, TNFRSF8 (CD30), and TNFRSF1B, which are described to have an activating role in a majority of other lymphomas, potentially suggesting a pleiotropic effect of these genes in lymphomagenesis." (PMID 38460675, 2024). "Differentially regulated genes were enriched for classical lymphoma driver genes downstream of the BCR, including MALT1 and CARD11, as well as NFATC2, TNFRSF13C (BAFF), and components of the NF-κB (RELB, IRAK1, BCL3, and TNFRSF1B) pathway." (PMID 39082968, 2024).
schizophrenia (9 papers, 2018 to 2026). A major psychotic disorder characterized by abnormalities in the perception or expression of reality. "Post-hoc analysis revealed that SNPs harbored in TNFRSF1B and CALCOCO1 independently conferred three-fold increase in TD risk, beyond clinical risk factors like Age of onset and Duration of illness to schizophrenia." (PMID 34103471, 2021).
Sézary syndrome (9 papers, 2015 to 2023). "For example, point mutations and genomic gains of the TNFR2 gene (TNFRSF1B) enhancing the activation of the non-canonical NF-κB signaling pathway have been described in 18% of patients with recurrent CTCL, for both mycosis fungoides and Sézary syndrome." (PMID 34712661, 2021).
Insulin resistance (8 papers, 2005 to 2025). Increased resistance towards insulin, that is, diminished effectiveness of insulin in reducing blood glucose levels. "PCOS group also exhibited an increased expression of androgen-mediated genes (SPI1 and ETS transcription factors) and genes associated with hyperlipidemia and insulin resistance (TNFRSF1B)." (PMID 40790236, 2025).
osteoporosis (7 papers, 2009 to 2025). A condition of reduced bone mass, with decreased cortical thickness and a decrease in the number and size of the trabeculae of cancellous bone (but normal chemical composition), resulting in increased fracture incidence. "Overall, rs3397 appears to downregulate TNFRSF1B, increase MAP infection, worsen inflammation, and cause osteocalcin deficiency and possibly osteoporosis in RA." (PMID 31817071, 2019). "Here, we studied the frequency and effects of SNPs in TNFα/TNFRSF1A/TNFRSF1B in RA including gene expression, MAP infection, and osteoporosis marker levels in blood (54 RA and 48 healthy controls)." (PMID 31817071, 2019). "In this study, we focused on investigating the interaction between SNPs in TNFα and its receptors (TNFRSF1A and TNFRSF1B), MAP infection, and active osteocalcin levels (an osteoporosis marker) in blood samples from RA patients." (PMID 31817071, 2019).
epilepsy (6 papers, 2016 to 2024). A brain disorder characterized by episodes of abnormally increased neuronal discharge resulting in transient episodes of sensory or motor neurological dysfunction, or psychic dysfunction. "TNFRSF1B could be triggered as a survival mechanism to compensate for the extensive neuronal cell death found in epilepsy-associated HS or its expression could enable the harmful consequences of TNFRSF1A activation." (PMID 27006531, 2016).
cognitive decline (5 papers, 2021 to 2025). "Furthermore, an interaction between the TNFRSF1B variant rs976881 and CSF sTNFR2 levels has been found to influence cognitive decline in AD." (PMID 40289873, 2025). "This suggests that the sTNFR2 levels are impacted by both CSF t-tau and p-tau levels and TNFRSF1B gene variant status, and mitigate cognitive decline over the short term but do not significantly impact cognitive outcomes over the longer term as the disease continues to evolve." (PMID 34276339, 2021).
glioma (5 papers, 2019 to 2025). A benign or malignant brain and spinal cord tumor that arises from glial cells (astrocytes, oligodendrocytes, ependymal cells). "Studies have shown that the immune checkpoint ligands ICOS, BTLA, TNFRSF1A, and TNFRSF1B all contribute to glioma immune evasion." (PMID 36882457, 2023). "We also found that IDHmt gliomas had a higher proportion of GAMs with an M1‐like phenotype (IDHmt: IDHwt = 90.62%: 75.86%), as supported by an augmented proinflammatory signaling consisting of GAM‐associated cytokines and receptors, such as TNF, TLR2, and TNFRSF1B." (PMID 37166058, 2023).
lupus nephritis (5 papers, 2022 to 2025). Glomerulonephritis in the context of systemic lupus erythematosus. "For example, genetic variants in genes expressed in the kidney (including TNFRSF1B, KLK1, KLK3, ACE, AGT, and APOL1) may result in increased susceptibility to kidney injury and, as a result, in progression to lupus nephritis." (PMID 39124752, 2024). "Normalized fluorescence intensity values for the five biomarkers (ALCAM, OPN, TNFRSF1B, VCAM1, and VSIG4) were compared between healthy controls (HCs) and lupus nephritis (LN) patient groups." (PMID 40047601, 2025).
Nephropathy (5 papers, 2019 to 2022). A nonspecific term referring to disease or damage of the kidneys. "TNFRSF1B binds to TNF-α and plays a critical role in immune regulation and kidney damage." (PMID 35370692, 2022).
cardiac hypertrophy (4 papers, 2020 to 2025). "In response to the increased blood pressure induced by transverse aortic constriction, mice lacking Tnfrsf1b showed worsened survival rates and increased cardiac hypertrophy, and the cardioprotective TNFR2 signaling has been linked to its effects in mitochondria." (PMID 33053859, 2020).
endometriosis (4 papers, 2013 to 2024). The growth of functional endometrial tissue in anatomic sites outside the uterine body. "TNFRSF1B encodes the TNFα receptor, TNFR2; both TNFR1 and TNFR2 have been investigated as potential biomarkers for endometriosis, given the pro-inflammatory roles of TNFα signaling." (PMID 38402336, 2024). "Enriched pathways in the endometriosis dataset included “Neuroinflammation and Glutamatergic Signaling”, with genes such as TNFRSF1B showing increased expression during decidualization." (PMID 38402336, 2024). "In the uM1 population, a significant increase in expression of inflammatory genes (TNFRSF1B, CEBPD) was detected in endometriosis, in keeping with previous reports of increased inflammation in endometriosis." (PMID 39198675, 2024). "Upregulation of IL1RL1, IL6ST, TNFRSF1B, and NR3C1 has been described in women with endometriosis." (PMID 38069001, 2023).
endothelial dysfunction (4 papers, 2011 to 2025). In vascular diseases, endothelial dysfunction is a systemic pathological state of the endothelium (the inner lining of blood vessels) and can be broadly defined as an imbalance between vasodilating and vasoconstricting substances produced by (or acting on) the endothelium. "For example, the concurrent elevation of adhesion molecules (ALCAM and VCAM1) alongside pro-inflammatory cytokines (TNFRSF1B and OPN) could provide deeper insights into endothelial dysfunction and immune activation in LN." (PMID 40047601, 2025).
glomerulonephritis (4 papers, 2022 to 2025). A renal disorder characterized by damage in the glomeruli. "However, the TNFRSF1B expression in the kidney has never been studied and does not appear to be expressed in IgA-dominant infection-related glomerulonephritis." (PMID 38291238, 2024).
lymph node metastasis (4 papers, 2010 to 2021). "Clinical response was determined by T class (an index of tumor size, p = 0.002), N class (lymph node metastasis, p = 0.007), M class (distant metastasis, p = 0.001) and disease stage (p < 0.001), but TNFRSF1B A1466G genotype was independent of these factors." (PMID 20646319, 2010). "Clinical response was predicted by tumor size (p = 0,002), lymph node metastasis (p = 0.007), distant metastasis (p = 0.001) and disease stage (p < 0.001), but TNFRSF1B A1466G genotype was independent of these factors." (PMID 20646319, 2010).